CD38 (CD38 molecule)
Diseases named in the same sentence as CD38 in open-access papers (continued):
Sharing a sentence is not in itself a finding about the gene and the disease.
lupus (continued). "Besides, NAD metabolism and its dysfunction via the enzyme CD38 are involved in the pathogenesis of rheumatologic diseases, including systemic sclerosis, systemic lupus erythematosus and rheumatoid arthritis." (PMID 35441488, 2022). "Besides, immune response, early phases of haematopoietic differentiation, rheumatoid diseases—systemic lupus erythematosus (SLE), rheumatoid arthritis (RA), loss of antioxidant potential—also lead to the increased expression of CD38." (PMID 36077708, 2022). "Of note, in a recent proof-of-concept study, two patients with systemic lupus erythematosus (SLE) refractory to multiple lines of therapy were successfully treated with anti-CD38 daratumumab, with long-term efficacy that was maintained with belimumab co-administration." (PMID 36618427, 2022). "However, the levels of the CD38 receptor, which functions as an NADase, is elevated in T cells of patients with lupus with increased disease activity, and the stimulation with CD38 antibodies results in the production of Th1 and Th2 cytokines." (PMID 35025762, 2022). "Besides, CD38 finds its role outside oncology in systemic lupus erythematosus and collagen-induced arthritis." (PMID 36077708, 2022). "The relevance to lupus is that abnormal NAD-dependent deacetylation could be reverted pharmacologically or with anti-CD38 therapy." (PMID 34504495, 2021). "In addition, these experiments provided evidence that CD38 promotes apoptosis of monocyte/macrophages in a TRMP2-dependent manner during experimental lupus." (PMID 33329591, 2020). "In this study, we investigated the role of CD38 in a pristane-induced murine model of lupus." (PMID 29463868, 2018). "In summary, CD38 enhances the development of pristane-induced lupus by regulating the cell death of Ly6Chi monocytes and Ly6Clo monocytes/macrophages in a TRPM2-dependent and ART2-independent manner that worsens the early inflammatory response in the peritoneum." (PMID 29463868, 2018). "Our results highlight the importance of the immunoregulatory role of CD38 in inflammation and in the development of systemic autoimmunity leading to lupus, which should be considered when designing CD38-specific therapies for the treatment of inflammatory and autoimmune diseases." (PMID 29463868, 2018). "Indeed, we have shown in the pristane-induced lupus model that in Cd38−/− mice there is reduced autoantibody production, type I IFN signature, and inflammatory signature compared to WT and Art2−/− mice." (PMID 30257456, 2018). "An anti-CD38 or other plasma cell/plasmablast targeting agent may also prevent/delay the progression of asymptomatic autoimmunity to a clinically classifiable lupus stage." (PMID 29720240, 2018). "Indeed, previous reports have noted an increase in the number of early B cells, memory B cells and CD38+ plasmablasts in lupus in both murine models and patient samples." (PMID 23826184, 2013). "For example, in autoimmune diseases like RA and SLE (systemic lupus erythematosus), decreased numbers or impaired function of CD38+ Bregs have been observed." (PMID 40453084, 2025). "This phase Ib/IIa study aimed to explore the safety, pharmacokinetics, pharmacodynamics, and preliminary efficacy of CM313, an anti-CD38 antibody, in patients with systemic lupus erythematosus (SLE)." (PMID 41290616, 2025). "Since CD38 expression is upregulated in SLE T cells and correlates with disease activity, our results implicate Rab4A as a potential driver of CD38 dysregulation in lupus." (PMID 40585226, 2025). "In another study, treating SLE patients with Ruplizumab eliminated their circulating CD38+ plasma cells and reduced their levels of anti-double stranded DNA, proteinuria, and Systemic Lupus Erythematosus Disease Activity Index (SLEDAI)." (PMID 39404385, 2024). "Previous studies of our group in Systemic Lupus Erythematosus (SLE) patients show increased CD38 surface expression in T cells and low levels of anti-CD38 autoantibodies in clinically active patients." (PMID 30257456, 2018).
lupus (continued). "Increased CD38 expression in T cells from patients with SLE may contribute to lupus pathogenesis because T cells produce Th1 and Th2 inflammatory cytokines when they are stimulated with CD38 antibodies." (PMID 39995666, 2025). "In the bm12-cGVHD lupus model, apoptosis is one of the most significant enriched KEGG pathways shown in WT PECs at both time points, and in Cd38-/- PECs 2 weeks after the allogeneic challenge." (PMID 39995666, 2025). "On the other hand, the NAD+-consuming enzyme CD38 responsible for the decline in NAD+ levels impaired cytotoxic CD8+ T cell responses and increased propensity to infections in patients with systemic lupus erythematosus (SLE)." (PMID 37165408, 2023). "In systemic lupus erythematosus (SLE) patients, the upregulation of CD38 expression in marginal zone-like IgD + CD27 + B cells has been reported, and the depletion of CD38 in pristane-induced lupus mouse model significantly improve the symptom." (PMID 36426217, 2022). "This study found a correlation between CD38 with FoxP3 expression and immunosuppressive molecules (CD69, IL-10, CTLA-4, and PD-1) in T-cells from lupus-prone mice (B6.MRL-Faslpr/J)." (PMID 34769406, 2021). "Furthermore, their ex vivo experiments showed that daratumumab effectively depletes plasma cells in peripheral blood mononuclear cells (PBMCs) and that CD38 inhibition can be a novel treatment option for both RA and systemic lupus erythematosus (SLE)." (PMID 31179321, 2019). "In a previous paper we have shown that the absence of CD38 had a strong effect in the development of the bm12 cGVHD lupus model." (PMID 39995666, 2025). "To assess the regulatory role of CD38 in T-cells from a lupus-prone mouse (B6.MRL-Faslpr/J), we examined FoxP3 expression in three different subsets of CD3+CD4+CD25+ and CD3+CD4+CD25− T-cells, gated according to CD38 expression." (PMID 34769406, 2021). "Taken together, the results of our study showed that the absence of CD38 plays a significant role in the development of the bm12 cGVHD lupus model." (PMID 34504495, 2021). "Similarly, ART2-/-CD38-/- and TRPM2-/-CD38-/- double KO mice were used to study the contribution of CD38 to pristane-induced lupus." (PMID 33329591, 2020). "Hence, our data suggest that CD38 deficiency protects mice from pristane-induced lupus in a TRPM2-dependent manner by reducing the number of intraperitoneal apoptotic cells, which are the primary source of autoantigens in this murine model of SLE." (PMID 29463868, 2018). "One possible explanation for the results of increased frequencies of CD5+CD1dhiCD19+ B cells in the context of the pristane lupus model has to do with the low proportion and numbers of peritoneal pDCs, and the decreased levels of IFN-α in Cd38−/− mice 2 weeks after pristane treatment." (PMID 30257456, 2018). "Consistently, and although CD38 has been described as an activation marker on immune cells, the increased levels of CD38 on the different subsets in SLE did not correlate with clinical activity as measured by the Systemic Lupus Erythematosus Disease Activity Index 2000 (SLEDAI-2K)." (PMID 33670902, 2021). "Finally, monocyte analyses in systemic lupus erythematosus patients revealed that, while all monocytes express CD38, high CD38 expression in the non-classical monocyte subpopulation is associated with disease." (PMID 30042766, 2018). "RA patients also expressed significantly more IgG+veCD27−ve B cells that lacked expression of CD24, CD38, and CD21, which are akin to double negative 2 (DN2) B cells known to be associated with more severe, active systemic lupus erythematosus (SLE)." (PMID 32265907, 2020).
autoimmune disease (51 papers, 2012 to 2026). A disorder resulting from loss of function or tissue destruction of an organ or multiple organs, arising from humoral or cellular immune responses of the individual to their own tissue constituents. "CD38 was also implicated in regulatory T cell function, particularly in the context of tumors and autoimmune diseases." (PMID 41009979, 2025). "However, since immunotherapies carry a risk of developing unprecedented complications, such as autoimmune diseases, it is important to decipher the precise nature and function of CD38 among various immune cell populations." (PMID 37180151, 2023). "However, as has been reported for other autoimmune diseases, CD38 may also actively suppress other pathogenic processes during IBD." (PMID 33329591, 2020). "CD38 is highly expressed on various immune cells, including long-lived plasma cells, making it a potential therapeutic target in autoimmune diseases." (PMID 41290616, 2025). "In recent years, several case series have been published demonstrating high efficacy and good tolerability for daratumumab intervention in several treatment-refractory autoimmune diseases, with a role emerging for anti-CD38 antibody therapy." (PMID 40703261, 2025). "On the other hand, the current predominant focus of CD38-targeting treatment lies in the field of autoimmune diseases (AIDs)." (PMID 38765013, 2024). "Except for helper T cells, CD38 expression in all cell types was higher in at least one autoimmune disease than in HCs." (PMID 38726007, 2024). "This expression profile of CD38, together with its role in inflammatory processes, make CD38 an interesting target in the context of autoimmune diseases." (PMID 38698867, 2024). "CD38: T cell surface protein that contributes to cell activation.HLA-DR: A marker of T cell activation that is also increased in autoimmune diseases." (PMID 38887284, 2024). "By influencing the NAD+/cADPR metabolism and the activity of T cells, CD38 allows for mitigating the immune response in autoimmune diseases." (PMID 36077708, 2022). "Both Gd-IgA1 and anti-Gd-IgA1 antibody production are believed to be driven by CD38+ plasma cells, a cell type that contributes to autoimmune disorders by producing high quantities of autoantibodies." (PMID 35628935, 2022). "Low levels of circulating CD24+CD38+cells were seen in patients with active autoimmune diseases such as active RA." (PMID 36661897, 2022). "Female gender, advanced stage disease, previous treatment, 11qdel, CD38 positive, and CAD are associated with an increased risk of autoimmune diseases." (PMID 34830959, 2021). "Better understanding of the specific effects and mechanisms by which CD38 modulates inflammation and autoimmune disease will require specialized tools and resources." (PMID 33329591, 2020). "Since these findings were reported, many studies have sought to understand the extent to which CD38 contributes to the development of inflammatory and autoimmune disease, via modulation of immune responses." (PMID 33329591, 2020). "In the following sections, we summarize the studies available on the role of CD38 during inflammation and autoimmune disease." (PMID 33329591, 2020). "Another possible limitation of using anti-CD38 antibodies in autoimmune diseases is that, as already mentioned, CD38 is also widely expressed by IL-10 producing regulatory B cells." (PMID 31892266, 2019). "Despite the fascinating perspectives of targeting CD38 in autoimmune diseases, there are also several potential limitations that should be underlined." (PMID 31892266, 2019). "In the future, it would be interesting to characterize the expression and function of CD38 and CD203a/PC-1 in other human autoimmune diseases." (PMID 29769837, 2018). "The application of IGJ as biomarker can potentially facilitate clinical development of anti-CD38 in autoimmune diseases." (PMID 29720240, 2018).
autoimmune disease (continued). "To evaluate the possibility of specifically targeting CD38 and plasma cells in patients with autoimmune disease, we evaluated the expression of CD38 across a spectrum of immune cell subpopulations in human PBMC samples." (PMID 29720240, 2018). "Expression of CD38 has been associated with a number of diseases, including HIV infection 46, 47, autoimmune diseases [e.g. systemic lupus erythematosus 48], type II diabetes mellitus 35, osteoporosis 49, and cancer." (PMID 26864107, 2016). "As CD5/CD1d are regulatory facrors in mouse models of inflammation and CD24/CD38 are involved in human autoimmune diseases, we assessed the expression of these markers in CD19+ B cells via flow cytometry." (PMID 26378021, 2015). "CD4+CD38+DR+ percentage was significantly higher in autoimmune disease controls as compared with thrombotic APS patients." (PMID 24982803, 2014). "Different studies in experimental murine models of inflammatory/autoimmune diseases reveal some discrepancies about the role of CD38 in the control of pathological immune responses." (PMID 22438945, 2012). "In recent years, increasing evidence has shown that the CD38 protein may play an indispensable role in autoimmune diseases." (PMID 40963504, 2025). "It is remarkable that CD38 may facilitate the development of inflammatory and autoimmune diseases by regulating immune response, and CMPK2 is reported to control NLRP3 inflammasome activation." (PMID 35359935, 2022). "Taken together, the preliminary efficacy and safety data on felzartamab in MN and the proof-of-concept results in r/r MM provide further support for clinical development of anti-CD38 antibody therapies in IgAN and highlight their potential application in other plasma cell-driven autoimmune diseases." (PMID 35628935, 2022). "Their data showed that activated lymphocyte morphology, high levels of IgG and beta-2-microglobulin, and CD38 and/or FMC7 increased expression may raise the risk of an autoimmune disorder in a CLL setting." (PMID 34830959, 2021). "A previous study in CD38-/- mice has revealed some autoimmune disorders in aged mice." (PMID 34769406, 2021). "Thus, we proposed that CD38 expression is vital to maintain Treg cells homeostasis and to prevent autoimmune disease." (PMID 34769406, 2021). "It is therefore reasonable to hypothesize that CD38 can be a target for the treatment of autoimmune diseases by depleting plasma cells specifically." (PMID 29720240, 2018). "A comprehensive analysis of CD38 expression on various immune cells in patients with autoimmune diseases could facilitate the dosing possibility of depleting only plasmablasts and plasma cells without affecting other potentially beneficial cells." (PMID 29720240, 2018). "Similarly to Tregs, the number of iNKT cells, that also possess regulatory properties in certain models of autoimmune diseases, is also reduced in CD38 KO mice." (PMID 22438945, 2012). "Therefore, it could be argued that the depletion of immunosuppressive and regulatory subtypes may limit the efficacy of anti-CD38 therapies, or, in worst cases, induce a flare of the autoimmune disease." (PMID 31892266, 2019). "However, the role of CD38 in the development of autoimmunity and its implications are still controversial, as is the role of regulatory B cells in patients with established autoimmune diseases, in which they have been shown to be already reduced and functionally impaired." (PMID 31892266, 2019). "While CD38‐targeting antibodies were initially developed to kill malignant plasma cells, these monoclonal antibodies may also abrogate the production of autoantibodies in autoimmune disorders and thereby reduce autoantibody‐dependent effector mechanisms." (PMID 26864107, 2016). "Considering especially the trends of current practice of CD38-targeting therapies, CM313 possesses great potential in the treatment of autoimmune diseases where expanding clinical demand remains far unmet." (PMID 38765013, 2024).
autoimmune disease (continued). "The mAbs used in field of autoimmune diseases mainly target CD20, CD19, CD22, CD38 and B-cell activating factor (BAFF)." (PMID 36855629, 2023). "Consistent with therapeutic effects of anti-CD38 therapy in SLE, anti-thymocyte antibody treatments that include CD38 antibodies suppress SLE and other autoimmune diseases." (PMID 30042766, 2018). "Here, we extend these previous observations by analyzing the contribution of CD38 to the pathogenesis of CIA, a paradigmatic model of autoimmune disease mediated by Th1 and Th17 lymphocytes." (PMID 22438945, 2012). "Given that monoclonal antibodies targeting CD38 appear to have a beneficial effect on SLE, CD38 may be an attractive target for cell therapy in autoimmune diseases." (PMID 41596238, 2026). "We found that a few cells were present in scMEP10, which is formed by activated (HLA-DR+CD38+) Ag+ CD8dim T cells expressing CD57 and CD11c; such population is typically present in autoimmune diseases, is expanded in an Ag-dependent manner and mainly produce IFN-γ38." (PMID 38553477, 2024). "In contrast, the expansion of CD38+ HLA-DR+ T cells and NK cells was not a characteristic of autoimmune diseases, including SLE, JDM, and nonsystemic JIA." (PMID 37751296, 2023). "Specifically, both C15:0 and metformin had significant, dose-dependent effects on lowering: HLA-DR in the 3C system relevant to cardiovascular disease and chronic inflammation; and CD38, CD69, and T cell proliferation in the SAg cell system relevant to autoimmune disease and chronic inflammation." (PMID 37960259, 2023). "There is no anti-CD38 mAb approved by FDA in autoimmune diseases at present." (PMID 36855629, 2023). "Peripheral blood lymphocytes from 30 patients with DM, 37 patients with other autoimmune diseases (15 cases of SLE, 15 cases of RA and 7 cases of pSS), and 23 healthy individuals were phenotypically analyzed by flow cytometry for their expression of CD19, CD24, and CD38 surface markers." (PMID 27270362, 2016). "IMGT/mAb-DB contains six mAbs against CD38, two of which have been approved by the FDA for cancer treatment; however, none reached the clinic yet in the field of autoimmune diseases." (PMID 38140161, 2023).